APP (amyloid beta precursor protein)
Diseases named in the same sentence as APP in open-access papers (continued):
Sharing a sentence is not in itself a finding about the gene and the disease.
amyloid (continued). "Consistent with the results of ELISA assay, both the number and area of amyloid plaque deposition in hippocampus and cortex of APP/PS1 mice significantly decreased when overexpressing miR-338-5p." (PMID 33087587, 2020). "To assess how Arg1 insufficiency in myeloid cells impacted amyloidosis, we crossbred LoxP Arg1 (Arg1fl/fl) mice with transgenic APP Tg2576 mice (APP+/−) to generate APP(+/−)/Arg1(fl/−) and APP(−/−)/Arg1(fl/−) (non-transgenic, nTg) mice." (PMID 33519806, 2020). "Considering that APP/E4 mice show earlier onset of amyloid pathology, the TREM2 effect on plaque growth in mice expressing this isoform is observed in mice younger than their APOE3 counterparts." (PMID 32703241, 2020). "The amount of cerebral amyloid deposits correlated with levels of the human APP transcript at 12 months." (PMID 31991578, 2020). "Our data show consistency with Hoet’s study, suggesting that HFD-induced insulin resistance promotes amyloidosis in brain and exacerbates cerebral AD-like pathological alterations in APP transgenic mice." (PMID 33291072, 2020). "It is well-known that in APP-transgenic mice, cognitive stimulation and voluntary exercise decrease amyloid deposition in the brain." (PMID 32977423, 2020). "Chronic infusion of BKB1R antagonist in transgenic mice expressing human amyloid precursor protein (APP) abolished amyloidosis, cerebrovascular arrest, and memory deficits." (PMID 33019732, 2020). "Constitutive overexpression of VIP in the hippocampus reduces inflammation and attenuates amyloidosis in transgenic PS1/APP mice, which present increased β-amyloid production associated with behavioral abnormalities." (PMID 32765225, 2020). "The β-amyloid peptides Aβ-40 and Aβ-42 are intrinsically disordered proteolytic fragments of amyloid-beta precursor protein and their aggregates constitute the principal components of the amyloid plaques." (PMID 31936201, 2020). "The amyloid plaques accumulate extracellularly in the brains of AD patients and are generated by sequential processing of the amyloid precursor protein, APP." (PMID 33282871, 2020). "Next, we assessed the presence of TTR and APP as well as amyloid structures in human CAVD tissue by immunohistochemistry and histology." (PMID 32987857, 2020). "We measured mouse general working memory by Y-maze and showed that APP mice demonstrated a decreased percentage of alternation (p < 0.0001), suggesting decreased working memory with amyloidosis." (PMID 33519806, 2020). "Amyloid plaques are composed of amyloid ß (Aß) peptides cleaved from the Amyloid Precursor Protein (APP)." (PMID 33551742, 2020). "Amyloid plaques consist of β-amyloid (Aβ) peptides, which are derived as a result of cleavage of the amyloid precursor protein (APP)." (PMID 31600883, 2019). "As the most drastic developmental changes in both myelination and cortical thickness have already taken by that age, this model was referred as mature-onset APP expression, which is in a context resembling closer the human sAD amyloid pathology." (PMID 31727182, 2019). "For example, epicatechin (a major component we identified in cat’s claw, which is also present in green tea) reduced amyloid plaque load in brains of APP/PS1 transgenic mice after oral administration." (PMID 30728442, 2019). "Consistently, we found that both the number and area of amyloid plaque deposition in hippocampus and cortex of APP/PS1 mouse brain were markedly ameliorated by miR-181a overexpression." (PMID 31467256, 2019). "Since ROCK1 inhibition reduced BACE1‐derived β‐CTF, it is concluded that β‐CTF decrease is the key contributor preventing amyloid formation and involved in ameliorating cognitive deficits in Y‐27632‐treated APP/PS1 mice." (PMID 31287605, 2019). "Together, these results suggest that a LPS elicited peripheral immune challenge affects amyloid deposition in aged APP/PS1 mice in an NLRP3‐dependent manner." (PMID 31359456, 2019).
amyloid (continued). "Assessment of AD-relevant phenotypes showed that the effects of the APP/PS1 transgenes are strain-dependent and sex-dependent, with significant differences in amyloid deposition, neuronal cell loss and cerebral amyloid angiopathy (CAA)." (PMID 31150388, 2019). "This evidence of oligomeric sAβ-induced synaptotoxicity has, however, come directly from transgenic developmental-onset mouse models of amyloidosis, i.e. the overexpression of APP starts from embryonic or very early postnatal developmental stage." (PMID 31727182, 2019). "MSC-RVG-Exo administration significantly alleviated memory deficits and effectively decreased Aβ levels and amyloid plaque loading in the brain of APP/PS1 mice." (PMID 31114624, 2019). "Certainly, triplication (i.e., the presence of three copies) of chromosome 21 in Down syndrome increases APP gene abundance and also the occurrence of clinical amyloidosis and dementia based on the classical amyloid/tau phosphorylation pathway." (PMID 30823541, 2019). "In order to evaluate the impact of oligomeric sAβ accumulation on the brain neuronal networks in mature mice, we used the inducible Tet-Off APP mouse model of amyloidosis (line 107) in which the APP overexpression can be controlled via a specific diet." (PMID 31727182, 2019). "ApoA-I-containing HDL can reduce amyloid pathology and astrocyte reactivity to parenchymal and vascular amyloid in APP/PS1 mice." (PMID 31084613, 2019). "Upon integrating MGLs within brain organoids derived from APP-mutant hiPSCs displaying overt amyloid pathology, APOE4 MGLs developed longer processes." (PMID 31856864, 2019). "Oleic acid is thought to reduce APP gene expression and can prevent amyloidosis in rodent AD animal models." (PMID 31485251, 2019). "Our intent was to identify, in anesthetized AD mice, brain network changes that anticipate the onset of amyloidosis, proceed with amyloid accumulation, but are distinct from those linked to the expression of either the PS2 or APP mutations." (PMID 31878336, 2019). "Accordingly, in APP-overexpressing transgenic mouse models of amyloidosis, the mutant APP is either the human transgene or a chimeric mo/huAPP transgene bearing humanized Aβ domain with single or multiple fAD-associated mutations." (PMID 31727182, 2019). "Intraperitoneal injection of IL-33 ameliorated synaptic impairment and amyloid pathology in APP/PS1 mice." (PMID 30953557, 2019). "Trisomy of the APP gene can be genetically reverted to diploid levels to slow down the features of amyloidosis in DS mouse models." (PMID 30823541, 2019). "CSF-1 treatment has been shown to improve memory deficits and ameliorate amyloid plaque burden in the APP/PS1 mice." (PMID 31822279, 2019). "We previously concluded that deletion of Tyrobp can slow or delay the progression of learning deficits in APP/PSEN1 transgenic mice during the early stages of amyloid deposition." (PMID 30283032, 2019). "The present study provides evidence that geniposide, a natural compound derived from the Gardenia fruit that acts as a GLP-1 agonist, attenuates amyloid plaque formation and cognitive impairment in the APP/PS1 mouse model of AD." (PMID 30684442, 2019). "To address this concern, we investigated sAβ effects on functional resting-state networks in transgenic mature-onset amyloidosis Tet-Off APP (TG) mice." (PMID 31727182, 2019). "Intracerebral inoculation of Aβ containing brain extracts into amyloid precursor protein (APP) transgenic mice was first shown to be sufficient to result in an Aβ amyloidosis in the recipient animals." (PMID 30483944, 2019). "To highlight brain network dysfunctions linked exclusively to amyloidosis, we also analyzed the tg lines PS2.30H and APPSwe, which carry the same mutations in PS2 or APP individually." (PMID 31878336, 2019).
amyloid (continued). "Beta-amyloid is generated by the sequential cleavage of beta (β) and gamma (γ) sites in the amyloid precursor protein (APP) by β- and γ-secretase enzymes and its accumulation can result from either a decreased Aβ clearance or increased metabolism of APP." (PMID 30498753, 2018). "Aβ, as the main component of the amyloid plaques in the AD brain, is derived from amyloid precursor protein (APP) processed sequentially by β- and γ-secretase." (PMID 29867325, 2018). "CX3CR1 deficiency in three different AD mouse models—APP/PS1, R1.40 and CRND8—reduced amyloid deposits and enhanced Aβ phagocytic ability by microglia." (PMID 30158892, 2018). "The administration of UCH-L1 protein fused to the transduction domain of HIV transactivator (TAT) protein into APP/PS1 model mice of AD provided a protective effect against amyloid-induced neurodegeneration in synaptic function and contextual memory." (PMID 29850612, 2018). "Crossing APP mutant mice with mice expressing mutant PS1 genes resulted in the dramatic development of amyloid pathology and memory deficits." (PMID 30618767, 2018). "Altogether, these data indicated that early and chronic A2AR blockade reduces the development of cortical amyloid burden in APP/PS1 mice." (PMID 30050407, 2018). "We found that CSP had higher bioavailability, improved spatial learning and memory, and reduced amyloid pathology in APP transgenic mouse." (PMID 29535835, 2018). "As a first model of amyloidosis, we used transgenic mice expressing human amyloid precursor protein (APP) and presenilin 1 (PS1)." (PMID 29472246, 2018). "Ablation of CX3CR1 in APP-transgenic mice led to reduced amyloid plaque burden most likely due to an increased phagocytic activity of CX3CR1-negative microglia in these mice." (PMID 29371603, 2018). "We assessed the effects of a multimodal botanical extract, DA-9803, on behavioral deficits in 5XFAD mice as well as amyloid pathology, neuronal calcium homeostasis, and neuroinflammation in APP/PS1 mice." (PMID 29378621, 2018). "Age-dependent spatial memory impairment in APP/PS1 has been shown to correlate with increased brain amyloid burden." (PMID 30050407, 2018). "An in vivo study demonstrated iron overload in APP/PS1 (amyloidosis) mouse model stimulated amyloidogenic processing and altered neuronal signaling to increase Aß plaque formation, leading to cognitive deterioration." (PMID 29593525, 2018). "On the other hand, effects of viral delivery of human ApoE assessed in APP transgenic mice showed reduced amyloid plaque load by ApoE2 and increased plaque load by ApoE4." (PMID 30541602, 2018). "The 5XFAD mouse, a widely used amyloid pathology model, overexpresses APP and PS1, displays aggressive amyloid pathology, and has been reported to exhibit ER stress." (PMID 30315100, 2018). "This agent was able to ameliorate spatial memory deficits in APP mice after the onset of amyloid deposition." (PMID 29208638, 2018). "When given at pre-plaque stage or after plaque deposition, an anti-mouse ApoE antibody decreased amyloid plaque load and improved brain functional connectivity and cognition in an APP transgenic mouse model." (PMID 30541602, 2018). "An increase in ADAM10 activity shifts the balance of APP processing toward APPs-alpha and protects the brain from amyloid deposition and disease." (PMID 28367112, 2017). "Amyloid plaques consist of extracellular aggregates of Aβ, which is a cleavage product derived from the amyloid precursor protein (APP) by β- and γ-secretase cleavage." (PMID 28401333, 2017). "Most importantly, we reported that intracerebroventricular IGF2 infusion ameliorates the amyloidosis and the cholinergic defect in the APP.PS1 mice." (PMID 28103298, 2017). "Beta amyloid protein is the proteolytic product of APP, which is anterogradely transported to the nerve terminals where amyloid plaques are more likely to be formed to regulate synaptic activity." (PMID 29176903, 2017).
amyloid (continued). "APP/PS1 double-transgenic mice treated with 3F5 mAb showed reduced memory loss, cognitive decline, and decreased levels of amyloid deposits in the brain." (PMID 28662102, 2017). "In our opinion, it is reasonable to assume that a dose of around 5 mg/kg/day of escitalopram would at least be equivalent to the effect of 8–10 mg/kg/day of citalopram, which is around the dose reported to effect amyloidosis in 7-month-old APP/PS1 mice." (PMID 28899417, 2017). "Here, we report that hAPP-transgenic models of amyloidosis devoid of endogenous mouse APP expression (mAPP-knockout / mAPPko) show increased amounts and higher speed of Aβ deposition than controls with mAPP." (PMID 28637503, 2017). "Compared with APP mice, less β-sheet amyloid plaques were observed in the hippocampus of APP/DcR3 mice as determined by thioflavin-S staining." (PMID 28438208, 2017). "High levels of iron have also been reported in the amyloid plaques in PS/amyloid precursor protein (APP) and APP [V717I] transgenic mice, resembling those seen in the brains of AD patients." (PMID 28360837, 2017). "To elucidate the effect of CatB on ß-amyloidosis we injected AAV-GFP or -CatB (1 × 109 vg/2 μl/shot) bilaterally into the hippocampus of three month-old APP/PS1 mice." (PMID 27966067, 2017). "Amyloid plaques are formed by amyloid-β (Aβ) peptides, generated by sequential enzymatic cleavages of amyloid precursor protein (APP) at the plasma membrane." (PMID 28806762, 2017). "Since PrP-amyloid plaques in p-CJDMM1 cases sometimes co-localize with APP, a well-established marker of axonal damage, PrPSc deposition in white matter eventually disrupts axon integrity." (PMID 29169405, 2017). "In the present study, we found that the intranasal administration of BMP9 significantly reduced the amyloid plaque load and Aβ levels in the brains of APP/PS1 mice, probably by promoting the efflux of Aβ mediated by LRP1." (PMID 28228716, 2017). "Inhibition of HDAC3 in the hippocampus attenuates spatial memory deficits, as indicated in the Morris water maze test, and decreases amyloid plaque load and Aβ levels in the brains of APP/PS1 mice." (PMID 28771976, 2017). "Subsequently we generated germ-free APP transgenic mice and found a drastic reduction of cerebral Aβ amyloid pathology when compared to control mice with intestinal microbiota." (PMID 28176819, 2017). "Here, our data provide the first evidence that the inhibition of HDAC3 by lentivirus‐mediated shRNA in the hippocampus attenuates spatial memory deficits and decreases amyloid plaque load and Aβ levels in 9‐month‐old APP/PS1 mice." (PMID 28771976, 2017). "The APP/PS1 mice develop amyloid pathology in the brain at an age of 6–7 months and closely recapitulate the pathological characteristics and progressive course of AD." (PMID 28603494, 2017). "The APP/PSEN1 TG mice were behaviorally characterized in multiple studies demonstrating amyloidosis as early as 4–6 months, which was linked to behavioral decrements in spatial learning, including decrements in WM due to synaptic changes." (PMID 29186131, 2017). "The conditional knockout of LRP1 in the neurons of APP/PS1 mice resulted in exacerbated amyloid pathology in the brain." (PMID 28228716, 2017). "The passive immunization with tau antibody 43D can also decrease APP, amyloid plaque load, and Aβ level." (PMID 28073379, 2017). "The APP/PS1 AD mouse is a model of cerebral amyloidosis, that rapidly develops amyloid associated pathologies with a robust gliosis and thus facilitates a quick readout of therapeutic effects." (PMID 28808293, 2017). "The characteristic age-dependent progressive amyloidosis in brain of the APP.PS1 mice was dramatically attenuated by an increased supply of choline during fetal and early postnatal development." (PMID 28103298, 2017). "During aging and or ischemia, accumulation of acidic metabolites decreases the pH which can affect the activity of enzymes related to APP processing affecting the amyloid plaque formation in AD." (PMID 27092072, 2016).
amyloid (continued). "Mice containing mutations in the amyloid precursor protein (APP) gene are the oldest and most widely studied models of AD and are used to investigate the role of APP, Aβ, and amyloidosis in neurodegeneration." (PMID 26923415, 2016). "A recent study reported that TFEB accelerates lysosomal degradation of amyloid precursor protein (APP), thus reducing Aβ generation and amyloid plaque pathogenesis." (PMID 27112200, 2016). "APP/PS1 mouse models of amyloidosis were passively immunized with SAR255952 or with a control (DM4) antibody from 3.5 months old until 8.5 months-old." (PMID 27047372, 2016). "Using the organoid model, we observed that amyloid pathology emerges prior to significant tau hyperphosphorylation in neural tissue derived from fAD patients carrying a duplication of the APP gene." (PMID 27622770, 2016). "Transgenic mouse models carrying genetic mutations of amyloid protein precursor (APP) and presenilin-1 (PS1) are commonly used to assess the pharmacodynamics of potential amyloidosis-lowering and pro-cognitive compounds." (PMID 27421117, 2016). "Amyloid plaques contain amyloid peptide amyloid-β42that has resulted from abnormal cleavage of amyloid precursor protein (APP)." (PMID 27524794, 2016). "In the initial iterations of bigenic APP/PS1dE9 mice, generated by crossing 2 independent lines of mice, cerebellar amyloid deposits were inconsistently observed, and present at a low frequency when observed." (PMID 26566997, 2015). "Levels of APP C99 were also higher in the amyloidosis group (103.2 ± 32.3% of GADPH levels) than control (70.9 ± 18.3%) (P = 0.009)." (PMID 25934480, 2015). "On the one hand, APP production and processing are unaltered despite prolonged overexpression of the transgene; and notably, the amyloid plaque burden was even reduced in crossed IL-1β XAT and APP/PS1 Tg mice." (PMID 25890375, 2015). "Amyloid plaques are highly enriched in aggregated amyloid-β (Aβ) peptide species, derived from the sequential proteolysis of the amyloid precursor protein (APP) by the β-site APP cleaving enzyme 1 (β-secretase) and the γ-secretase complex." (PMID 26308941, 2015). "It is the most common form of dementia and has been characterized by the cerebral deposition of β-amyloid (Aβ) peptides as amyloid plaques which are generated from amyloid precursor protein (APP) by β and γ secretases." (PMID 25815277, 2015). "Amyloid plaques are mainly composed of amyloid‐β (Aβ) peptides, typically 1–40 and 1–42 amino acids in size, that are produced from the cleavage of the amyloid precursor protein (APP) by secretases." (PMID 25556298, 2015). "Treatment with NB-360, a potent and brain penetrable BACE-1 inhibitor can completely block the progression of Aβ deposition in the brains of APP transgenic mice, a model for amyloid pathology." (PMID 26336937, 2015). "Amyloid plaques are formed from the amyloid β peptide (Aβ), which is a proteolytic product of the amyloid precursor protein (APP)." (PMID 26618502, 2015). "Iron was shown to play a role in the contrast in amyloid in human AD brains on imaging, yet plaques in APP/PS1 mice were as easily observed despite having significantly less Fe." (PMID 25400539, 2014). "Conditional deletion of Lrp1 gene in vascular smooth muscle cells in amyloid model APP/PS1 mice accelerated brain Aβ accumulation and exacerbated Aβ deposition as amyloid plaques and CAA, without affecting Aβ production." (PMID 23908553, 2014). "Aβ, which is the core component of the amyloid plaques, is produced by subsequent cleavage of a large transmembrane protein—amyloid precursor protein (APP)—by two different proteolytic enzymes β- and γ-secretase." (PMID 25019089, 2014). "In conclusion, in our study we report diurnal dynamics of APP metabolites diminished with age, and, only for Aβ, were further attenuated with amyloidosis." (PMID 24646516, 2014). "In summary, the β55 aptamer binds amyloid plaques in both ex vivo human AD brain tissue and in vivo APP/PS1 transgenic mice." (PMID 24587111, 2014).